MORF4L1 (mortality factor 4 like 1)
Description:
Component of the NuA4 histone acetyltransferase (HAT) complex which is involved in transcriptional activation of select genes principally by acetylation of nucleosomal histones H4 and H2A. This modification may both alter nucleosome - DNA interactions and promote interaction of the modified histones with other proteins which positively regulate transcription. This complex may be required for the activation of transcriptional programs associated with oncogene and proto-oncogene mediated growth induction, tumor suppressor mediated growth arrest and replicative senescence, apoptosis, and DNA repair. The NuA4 complex ATPase and helicase activities seem to be, at least in part, contributed by the association of RUVBL1 and RUVBL2 with EP400. NuA4 may also play a direct role in DNA repair when directly recruited to sites of DNA damage. As part of the SIN3B complex represses transcription and counteracts the histone acetyltransferase activity of EP300 through the recognition H3K27ac marks by PHF12 and the activity of the histone deacetylase HDAC2. SIN3B complex is recruited downstream of the constitutively active genes transcriptional start sites through interaction with histones and mitigates histone acetylation and RNA polymerase II progression within transcribed regions contributing to the regulation of transcription. Required for homologous recombination repair (HRR) and resistance to mitomycin C (MMC). Involved in the localization of PALB2, BRCA2 and RAD51, but not BRCA1, to DNA-damage foci.
Synonyms: MRG15; FWP006; MORFRG15; HsT17725; Eaf3; MEAF3; S863-6
Tractability: Small molecule: it has a high-quality binding pocket. PROTAC: ubiquitination databases record sites on it; its protein half-life has been measured.
Gene: Protein-coding gene on chromosome 15 (78,810,487 to 78,903,078, forward strand). Ensembl gene ENSG00000185787.
Subcellular location: Nucleus
Subcellular location (Human Protein Atlas): Nuclear speckles
Pathways (Reactome):
Chromatin organization: HATs acetylate histones
Gene Ontology:
Molecular function: protein binding; chromatin binding
Biological process: double-strand break repair via homologous recombination; positive regulation of double-strand break repair via homologous recombination; regulation of cell cycle; positive regulation of DNA-templated transcription; regulation of apoptotic process; regulation of double-strand break repair; regulation of transcription by RNA polymerase II; chromatin organization; regulation of DNA-templated transcription
Cellular component: NuA4 histone acetyltransferase complex; nuclear speck; nucleosome; Sin3-type complex; nucleoplasm; nucleus
Genetic constraint (gnomAD): Loss-of-function variants: 3 observed, 28.57 expected, observed/expected ratio (o/e) 0.1, 90% interval 0.047 to 0.27. The upper end of that interval is the gene's LOEUF score, 0.27, which puts it in group 1 of 6, group 1 being the genes least tolerant of losing a copy. Missense variants: 145 observed, 265.31 expected, observed/expected ratio (o/e) 0.55, 90% interval 0.48 to 0.63. Synonymous variants: 85 observed, 99.44 expected, observed/expected ratio (o/e) 0.85, 90% interval 0.72 to 1.02.
Homologues: Orthologues: mouse Morf4l1 (100% identical), macaque MORF4L1 (99% identical), dog MORF4L1 (99% identical), pig MORF4L1 (99% identical), rat Morf4l1 (99% identical), guinea pig Morf4l1 (98% identical), tropical clawed frog morf4l1 (89% identical), zebrafish morf4l1 (88% identical), Drosophila melanogaster MRG15 (51% identical). Paralogues in human: MORF4L2 (67% identical), MSL3 (35% identical), MSL3B (20% identical).
Diseases named in the same sentence as MORF4L1 in open-access papers:
MORF4L1 is named in the same sentence as 20 diseases in open-access papers, as found by Europe PMC text mining. Sharing a sentence is not in itself a finding about the gene and the disease. The quoted sentences say what the papers report.
breast carcinoma (3 papers, 2011 to 2024). "Finally, we found three PGx-eQTL genes that were shared between our breast cancer GWAS and the GWAS catalog traits of cancer and hormone levels, namely SNX13, HLA-DQB2, and MORF4L1." (PMID 38965614, 2024).
colorectal cancer (2 papers, 2004 to 2026). A primary or metastatic malignant neoplasm that affects the colon or rectum.
pneumonia (2 papers, 2020). An acute, acute and chronic, or chronic inflammation focally or diffusely affecting the lung parenchyma, caused by an infection in one or both of the lungs (by bacteria, viruses, fungi, or mycoplasma.). "There is however an increase in the expression of Morf4l1 in humans with pneumonia and an upregulation in lung epithelia on getting exposed to P. aeruginosa or lipopolysaccharide (LPS)." (PMID 32731491, 2020). "In a mouse model of pneumonia induced by P. aeruginosa, it was observed that Morf4l1 is stabilized due to acetylation that protects it from Fbxl18-mediated degradation." (PMID 32731491, 2020). "Mortality factor 4 like 1 protein regulates chromatin remodeling and mediates epithelial cell death in a mouse model of pneumonia." (PMID 32719718, 2020).
Alzheimer disease (1 paper, 2019). A progressive, neurodegenerative disease characterized by loss of function and death of nerve cells in several areas of the brain leading to loss of cognitive function such as memory and language. "GSEA results showed that samples with deficiency of MTOR, CRISPLD2 or MORF4L1 showed consistent down-regulation in pathways of Alzheimer’s disease, Parkinson’s disease and Huntington’s disease." (PMID 31219803, 2019).
Obesity (1 paper, 2025). Accumulation of substantial excess body fat. "In the obesity signature, eight genes were found to possess regulatory functions: COPS5, GATA2, MORF4L1, OPTN, PFDN5, SETBP1, TCF4, and ZBTB16." (PMID 40102990, 2025).
cancer (4 papers, 2011 to 2025). A tumor composed of atypical neoplastic, often pleomorphic cells that invade other tissues. "Parallel to FA, we hypothesized that germline mutations or common variants in MORF4L1 may confer moderate/low risk of BrCa and/or modify cancer risk among BRCA1 and/or BRCA2 mutation carriers." (PMID 21466675, 2011). "Experimentally, MORF4L1 was demonstrated to enhance cancer stemness by activating the Hedgehog signaling pathway, as supported by both in vitro and in vivo assays." (PMID 39757177, 2025). "Nevertheless, given the extremely low frequency of high/moderate-penetrance mutations of other components of the FA/BrCa pathway and the possible involvement in other cancer types, further investigation of MORF4L1 may be warranted." (PMID 21466675, 2011). "This was further supported by the significant changes in cancer stem cell (CSC) marker expression (CD133, CD24, EPCAM) corresponding to MORF4L1 expression levels." (PMID 39757177, 2025). "MORF4L1 is a member of a gene family related to MORF4 and is involved in cancer cell senescence." (PMID 37365518, 2023).
tumor (3 papers, 2024 to 2026). "Pseudotime trajectory analysis further confirmed that RT exposure drives tumor cells toward a highly resistant state, marked by a distinct increase in MORF4L1 expression." (PMID 41751172, 2026). "In a subcutaneous tumor model using nude mice, MORF4L1 overexpression accelerated tumor growth and tumorigenesis, whereas its silencing had an inhibitory effect." (PMID 39757177, 2025). "Lenvatinib treatment studies demonstrated MORF4L1's influence on drug resistance and tumor recurrence, with knockdown cells showing sustained tumor growth inhibition." (PMID 39757177, 2025). "While antibody staining of this TMA for MORFL1 was less successful resulting in low numbers, some correlation was seen for MORF4L1 with Gleason grade albeit with low tumour numbers." (PMID 39267821, 2024). "High-resolution scRNA-seq analysis of the tumor cell compartment revealed that the MORF4L1-high subpopulation exhibited significant enrichment in DNA damage repair (DDR) pathways, heightened activity of multiple pro-survival metabolic pathways, and robust signatures of immune evasion." (PMID 41751172, 2026). "Through Real-Time Quantitative Reverse Transcription PCR (qRT-PCR), Western Blot, and immunohistochemistry analyses on tumor and adjacent normal liver tissues, we observed significantly higher MORF4L1 expression levels in HCC tissues at both mRNA and protein levels." (PMID 39757177, 2025). "Our study demonstrates that MORF4L1 promotes HCC initiation and progression through in vitro sphere formation and in vivo tumor models." (PMID 39757177, 2025). "Additionally, MORF4L1 interacts with proteins such as ASH1L, activating histone methyltransferase activity and potentially altering tumor chromatin structure." (PMID 39757177, 2025). "MORF4L1 interacts with the BRCA multiprotein complex, and thereby mediates DNA damage response and repair of DNA double-strand breaks, having therefore a potential tumour suppressor role, through interaction with PALB2 and BRCA, members of the DNA damage repair signalling pathway." (PMID 39267821, 2024).
MORF4L1 also shares sentences with these, for which no sentence is quoted: Azoospermia (2 papers); colon carcinoma (1); Fanconi anemia (1); Hepatic steatosis (1); hepatocellular carcinoma (1); Huntington disease (1); Hyperchloremia (1); Hypercholesterolemia (1); metastasis (1); Parkinson disease (1); prostate carcinoma (1); schizophrenia (1); steatosis (1).